NIT1 (nitrilase 1)
Diseases named in the same sentence as NIT1 in open-access papers:
NIT1 is named in the same sentence as 20 diseases in open-access papers, as found by Europe PMC text mining. Sharing a sentence is not in itself a finding about the gene and the disease. The quoted sentences say what the papers report.
insulinoma (5 papers, 2011 to 2019). "By exposing NIT1 insulinoma cells and rat islets to a cocktail of pro-inflammatory cytokines (TNFα and IL1β), we mimicked inflammatory signaling as seen by JNK and NFκB activation and increased mRNA levels of TNFα, IL1β and NOS2a." (PMID 24974801, 2014). "To address this issue, we stimulated β cell antigen-specific T cells in NOD mice at 6 weeks of age with an intraperitoneal injection of NIT1 (NOD mice insulinoma cell line) lysates along with ATG or isotype IgG treatment." (PMID 23237483, 2012). "Moreover, the GPR40 agonists could reduce inflammatory signaling, such as NF-κB, IL-1β, TNF-α, and NOS2α, in the mouse NIT1 insulinoma cells and rat islets that are under chronic inflammatory conditions and LPS-induced activation of IKK in BV2 cells." (PMID 30981281, 2019). "This is in accordance with the extrinsic type I model of Fas-mediated apoptosis that proceeds independent of the mitochondria, and with Fas-mediated killing mechanisms previously identified in the NIT-1, NOD insulinoma cells, and primary NOD islets." (PMID 21738580, 2011).
colorectal cancer (4 papers, 2018 to 2025). A primary or metastatic malignant neoplasm that affects the colon or rectum. "The study shows that Nit1 contribute to the progression of colorectal cancer through regulating TGFβ1-Smad2/3 signaling pathway." (PMID 40740246, 2025). "In Lin's study, Nit1 expression in colorectal cancer cells was significantly reduced compared to adjacent normal epithelial cells." (PMID 40740246, 2025). "In colorectal cancer, the tumor suppressor gene NIT1 is realized by activating the SMAD2/3 signaling pathway." (PMID 36969909, 2023). "Here, we showed that NIT1 was significantly downregulated in colorectal cancer tissues compared with that in adjacent normal tissues." (PMID 29449642, 2018). "In this study, we confirmed the specific effects of NIT1 in the regulation of colorectal carcinoma cell proliferation." (PMID 29449642, 2018).
lung carcinoma (3 papers, 2016 to 2025). "In this study we aimed to determine the role of Nit1 in a transgenic mouse lung cancer model driven by a G12D Kras mutation." (PMID 26967383, 2016). "In our study, Nit1 expression was found to be significantly associated with lung cancer progression which indicates Nit1 may have different function in different tumors." (PMID 40740246, 2025). "Significantly reduced cell survival post Nit1 knockdown combined with cisplatin treatment in resistant A549 indicated that Nit1 deficiency may sensitize cisplatin response in human lung cancer." (PMID 26967383, 2016). "Reductions in cell survival indicate that Nit1 deficiency might sensitize cisplatin response in human lung cancer." (PMID 26967383, 2016). "We examined Nit1 expression in lung tissues and lung cancer tissues using both immunohistochemistry and western blot and both studies proved a higher level of Nit1 expression in cancer tissues compared to normal tissues." (PMID 40740246, 2025). "We detected Nit1 expression using Western blot in lung cancer cell lines including A549, H460, H661, H1299, LK2, PC9, and SK, and bronchial epithelial cell line HBE." (PMID 40740246, 2025). "H&E staining of Nit1+/+:KrasG12D/+ vs. Nit1−/−:KrasG12D/+ mice lung lesions were analyzed by a pathologist who specializes in lung cancer." (PMID 26967383, 2016). "To determine the impact of Nit1 in mediating therapeutic effects against lung cancer, we knocked down Nit1 through siRNA and followed with cisplatin treatment on the relatively cisplatin resistant human lung cancer cell line A549." (PMID 26967383, 2016). "We confirmed Nit1 expression in multiple human NSCLCs cancer cells and investigated the relevance of Nit1 to human lung cancers through TMAs." (PMID 26967383, 2016). "Our findings are consistent with the datasets of Oncomine, so we further investigated lung cancer cell survival post gene NIT1 knock down." (PMID 26967383, 2016). "One is the impact on apoptosis and cell cycle pathways in lung cancer cells, and the second is the interaction of the immune system and lung cancer cells as Nit1 has been reported as a negative regulator in primary T cells." (PMID 26967383, 2016). "Our study further proved that Nit1 may promote lung cancer cell proliferation and invasion through regulating epithelial-to-mesenchymal transition (EMT) related molecules and cyclins." (PMID 40740246, 2025). "However, the significance of Nit1 in lung cancer tissues and the molecular mechanism of its role in lung cancer is unclear." (PMID 40740246, 2025). "In addition, cisplatin response was enhanced in human lung cancer cells when Nit1 was knocked down and Nit1−/−:KrasG12D/+ tumors showed increased sensitivity to cisplatin in vivo." (PMID 26967383, 2016). "Furthermore, we found that Nit1 is highly expressed in human lung cancer tissues and cell lines and use of siRNA against Nit1 decreased overall cell survival of lung cancer cells in culture." (PMID 26967383, 2016). "To investigate whether Nit1 deficiency may promote or inhibit the development of NSCLCs, we knocked out Nit1 in KrasG12D/+ mice lung cancer model background." (PMID 26967383, 2016). "Based on these data, Nit1 may modulate growth patterns in lung cancer cells and maybe a new target for NSCLCs treatment in future." (PMID 26967383, 2016). "To determine whether lung cancer is dependent upon a high level of Nit1 expression, we tested lung cancer cell survival following Nit1 knockdown through siRNA using a specific siRNA smart pool." (PMID 26967383, 2016). "The culmination of these data led us to investigate the role that Nit1 may have in modulation of lung cancer." (PMID 26967383, 2016). "However, positive staining of Nit1 in lung cancer cells is more prevalent especially in squamous cell carcinoma (97.5%, 4C upper) and adenocarcinoma (97.7%, 4C upper)." (PMID 26967383, 2016).
lung carcinoma (continued). "Despite the early descriptions of Nit1 potentially functioning like a tumor suppressor when overexpressed, our data showed that Nit1 knockdown could decrease cell viability in various lung cancer cell lines and lung tumorigenesis was significantly suppressed in Nit1 knockout KrasG12D/+ mice." (PMID 26967383, 2016). "We also used Western blot and immunofluorescent staining to detect Nit1 expression in cells including bronchial epithelial cell HBE and lung cancer cells in vitro." (PMID 40740246, 2025). "Our data showed that knocking down NIT1, but not NIT2, can decrease cell viability in various lung cancer cell lines, and that it can be rescued after NIT1 expression levels were restored with recombinant human Nit1 adenovirus." (PMID 26967383, 2016). "Increased Nit1 abundance in NSCLCs and Nit1 dependent lung cancer cell survival implied that the NIT1 gene could not be a suppressor in cultured human lung cancer cell lines." (PMID 26967383, 2016). "All these information suggest that gene NIT1 may function independently and may not be suppressor in human lung cancer." (PMID 26967383, 2016).
lymph node metastasis (2 papers, 2021 to 2025). "Expression of Nit1 was significantly associated with advanced TNM stages, lymph node metastasis and poor clinical outcome of the patients (60.70 ±5.48 vs 30.83 ± 4.88) (p<0.05)." (PMID 40740246, 2025). "NIT1 expression in NSCLC cells was significantly associated with poor differentiation of cancer cells, advanced TNM stages (III versus I+II), lymph node metastasis and poor clinical outcome of the patients ((60.70 ±5.48 vs 30.83 ± 4.88 months) (p < 0.05)." (PMID 40740246, 2025). "In order to know whether c‐Myc activation is associated with lymph node metastasis in pNET, we evaluated the effect of c‐Myc on VEGFC expression in pNET cells (QGP‐1 and NIT‐1)." (PMID 33128283, 2021).
squamous cell carcinoma (2 papers, 2016 to 2025). A carcinoma arising from squamous epithelial cells. "Quantitation of the Nit1 staining amongst distinct human lung tumors demonstrated an approximately 2-fold increase of Nit1 staining intensity in squamous cell carcinoma (p<0.01) and 3-fold increase in adenocarcinoma (p<0.0001) over non-malignant lung tissues." (PMID 26967383, 2016).
glioma (1 paper, 2024). A benign or malignant brain and spinal cord tumor that arises from glial cells (astrocytes, oligodendrocytes, ependymal cells). "Analysis of Differentially Expressed Genes (DEGs) revealed significant upregulation of several genes in recurrent glioma, including NF1, NIT1, SCXB, and VCAN." (PMID 39554845, 2024).
iron deficiency (1 paper, 2023). "The findings of this study, which revealed that AHA2 and NIT1 were carbonylated under iron deficiency, appeared counterintuitive." (PMID 37298684, 2023). "There is limited evidence concerning AHA proteins undergoing another form of PTM other than phosphorylation, but we speculate that the carbonylation of AHA2 and of NIT1 under iron deficiency may serve to modulate their activity and abundance." (PMID 37298684, 2023).
lung diseases (1 paper, 2016). "In the 5/10 non-malignant lung tissues (from patients with non-malignant lung diseases), weakly Nit1 staining (expression score ~0.6) can be identified within the pneumocytes and macrophages (4C lower)." (PMID 26967383, 2016).
non-small cell lung carcinoma (1 paper, 2025). A group of at least three distinct histological types of lung cancer, including non-small cell squamous cell carcinoma, adenocarcinoma, and large cell carcinoma. "Immunohistochemistry study shows that expression of Nit1 was elevated in non-small cell lung cancer compared to normal lung epithelial cells including submucosal glands and bronchial epithelial cells (p<0.05)." (PMID 40740246, 2025). "In this study, we investigate the expression of Nit1 in human non-small cell lung cancer." (PMID 40740246, 2025).
pancreatic cancer (1 paper, 2024). "To investigate the role of MGMT in PanNET progression, we examined the expression level of MGMT in various human and mouse pancreatic cancer cell lines (SPNE1, NIT‐1, QGP‐1, Beta‐TC6, MIN6, and Bon‐1)." (PMID 39041891, 2024).
tumor (8 papers, 2016 to 2025). "KDMC5 and PHF20 are both involved in chromatin remodeling and transcriptomic regulation, while NIT1 is associated to tumor suppressor functions." (PMID 38501112, 2024). "Similar to Fhit, an enzymatic inactive Nit1 protein with a Cys to Ala mutation within the Glu-Lys-Cys catalytic triad revealed a tumor suppressor activity comparable to wildtype Nit1." (PMID 36766695, 2023). "We found reduced tumor lesions in Nit1 deficient KrasG12D/+ mice and then confirmed that human NSCLCs have high levels of Nit1." (PMID 26967383, 2016). "Human Nit1 was identified during the characterization of the tumor suppressor Fhit when it turned out that in D. melanogaster and C. elegans Fhit is expressed as a NitFhit fusion protein." (PMID 36766695, 2023). "Distinctly decreased expression of NIT1 was observed in 84% (58/69) of CRC tumour tissues compared with that in adjacent normal tissues." (PMID 29449642, 2018). "Based on these observations, Fhit and Nit1 were defined as Rosetta-Stone proteins with a postulated common tumour suppressive function, although a direct interaction of both proteins has not been shown till now." (PMID 27462437, 2016). "The total tumor volume was decreased in some Nit1+/+:KrasG12D/+ mice, but more than half of them had persistent tumor growth, whereas all Nit1−/−:KrasG12D/+ mice demonstrated significant tumor shrinkage." (PMID 26967383, 2016). "Nit1−/−:KrasG12D/+ mice have fewer and smaller lung lesions on CT with a 5-fold reduction of total tumor volume (median) compared with Nit1+/+:KrasG12D/+ mice (p<0.01)." (PMID 26967383, 2016). "Micro-CT scans and gross tumor measurements demonstrated a 5-fold reduction in total tumor volumes compared to Nit1+/+KrasG12D/+ (p<0.01)." (PMID 26967383, 2016). "Next, we measured the weight of tumor-bearing lungs as well as dissected tumors from mice of the two genotypes and demonstrated that Nit1+/+:KrasG12D/+ mice have a heavier tumor load." (PMID 26967383, 2016). "Surprisingly, Nit1−/−:KrasG12D/+ mice showed significantly decreased tumor burden (lesions, volume, lung and tumor weight) and significant life extension compared with Nit1+/+:KrasG12D/+." (PMID 26967383, 2016). "All tumor-bearing Nit1−/−:KrasG12D/+ mice demonstrated tumor shrinkage, whereas more than half of the Nit1 wild-type group had persistent tumor growth as shown by the waterfall plot." (PMID 26967383, 2016). "At present, the role of nit1 in tumor is mainly based on the research in mice." (PMID 40740246, 2025). "Moreover, an additive effect of Nit1 and Fhit double knockout on tumor formation was observed compared to single gene knockout animals." (PMID 36766695, 2023). "Subsequently, we assessed the effect of NIT1 on tumour growth in a nude mouse xenograft model." (PMID 29449642, 2018). "NIT1 protein has been reported to be a potential tumour suppressor in tumour progression." (PMID 29449642, 2018). "The expression level of NIT1 was divided into a high-expression group (n = 19) and a low-expression group (n = 50) to investigate the relationship between NIT1 expression levels and the clinicopathological characteristics of tumour tissue samples." (PMID 29449642, 2018). "Currently, little is known about the mechanisms of Nit1 tumour suppressor function." (PMID 27462437, 2016). "The number of pleural (p<0.001) or dissected tumor nodules (p<0.05) was significantly reduced in the Nit1−/−:KrasG12D/+ mice in comparison to Nit1+/+:KrasG12D/+ mice; in addition, the size of tumor nodules are much smaller in Nit1−/−:KrasG12D/+ mice (2B middle)." (PMID 26967383, 2016). "However, little is known about the specific role of NIT1 in tumour development and progression." (PMID 29449642, 2018). "However, whether NIT1 can be used as a universal biomarker or prognostic predictor for neoplasm needs further investigation." (PMID 29449642, 2018). "We demonstrated that NIT1 suppresses CRC cell proliferation in vitro and tumour growth in vivo." (PMID 29449642, 2018).
cancer (4 papers, 2016 to 2025). A tumor composed of atypical neoplastic, often pleomorphic cells that invade other tissues. "In oesophageal adenocarcinoma, a loss of Nit1 expression was observed in 48% of the cases, suggesting a role in human cancer development." (PMID 27462437, 2016). "Western blot also shows elevated expression of Nit1 in cancer tissues compared to adjacent normal lung tissues (p<0.05)." (PMID 40740246, 2025). "The positive rate of NIT1 expression in cancer tissues (64.5%, 60/93) was significantly higher than that in normal lung epithelial cells (17.1%, 6/35) (p < 0.05)." (PMID 40740246, 2025). "Western blot study showed that overexpression of NIT1 in H1299 cells significantly regulated EMT-related molecules and cyclins which are associated cancer cell proliferation and invasion." (PMID 40740246, 2025). "We also detected NIT1 expression in lung and cancer tissues using Western blot which showed that NIT1 was increased in cancer tissues compared to adjacent lung tissues (p < 0.05)." (PMID 40740246, 2025). "Overexpression of Nit1 in H1299 cells significantly promoted cancer cell proliferation and invasion in vitro (p<0.05)." (PMID 40740246, 2025). "We focus on the clinicopathological significance of Nit1 expression in cancer tissues in vivo and the related molecular regulation in cancer cells in vitro." (PMID 40740246, 2025). "The immunohistochemistry study in cancer cells and immunofluorescent staining both indicate that Nit1 expression was mainly found in cytoplasm." (PMID 40740246, 2025). "Overexpression of NIT1 using transfection of NIT cDNA clones in H1299 cells significantly promoted cancer cells proliferation (MTT and colony formation studies) and invasion (Transwell study)." (PMID 40740246, 2025). "NIT1 expression was mainly detected in cytoplasm of normal lung epithelial cells and cancer cells." (PMID 40740246, 2025). "Nitrilase homolog 1 (Nit1) is a member of the carbon-nitrogen hydrolase family whose function in human cancer is largely unknown." (PMID 40740246, 2025). "We relied on Oncomine, a cancer microarray database and web-based data-mining platform, to identify the expression level of NIT1 in CRC tissues, the results indicated that NIT1 was significantly downregulated in CRC tissues compared with that in adjacent normal tissues (p < 0.001)." (PMID 29449642, 2018). "The function of Nit1 in human cells including cancer cells is largely unknown." (PMID 40740246, 2025). "We used Western blot and immunofluorescent staining to detect NIT1 expression in cell lines including lung epithelial HBE cells and cancer cells including A549, H1299, LK2, SK, PC9, H460 and H661 cells in vitro." (PMID 40740246, 2025). "Therefore, we investigated whether Nit1 expression is altered in human cancer." (PMID 27462437, 2016). "Our study confirmed that Nit1 regulates EMT-related molecules and cyclins, which may explain its function in regulating cancer cell proliferation and invasion." (PMID 40740246, 2025).
infection (4 papers, 2015 to 2024). The state of being infected such as from the introduction of a foreign agent such as serum, vaccine, antigenic substance or organism. "After infection with PstDC3000, NIT1/2/3 catalyzes the biosynthesis of auxin, thereby triggering certain disease-related responses." (PMID 39684605, 2024). "Upon infection with clubroot disease, Arabidopsis exhibits increased expression of NIT1 and NIT2 in its roots." (PMID 39684605, 2024). "Following PstDC3000 infection, NIT1/2/3 facilitate auxin biosynthesis, triggering certain disease responses." (PMID 39684605, 2024). "Transformation of A. thaliana plants with nitrilase 1 with antisense direction (aNIT1) exhibited a reduced infection rate cogmpared to wild type plants." (PMID 32756478, 2020). "In Hornet and Alister roots, a contrasting behavior was observed in the expression levels of NIT1, the auxin biosynthetic gene that is most commonly involved in the response to infection." (PMID 30551560, 2018). "It is hypothesized that upon Arabidopsis infection with PstDC3000, NIT1/2/3 preferentially catalyze aliphatic glucosinolates to bolster plant immunity against pathogens." (PMID 39684605, 2024).
bacterial infection (1 paper, 2017). "It has been shown that NIT1 as well as NIT2 expression is induced in the course of bacterial infection with Plasmodiophora brassicae." (PMID 28174581, 2017).
movement disorder (1 paper, 2024). Neurological conditions resulting in abnormal voluntary or involuntary movement, which may impact the speed, fluency, quality and ease of movement. "Furthermore, biallelic variants in NIT1 have been recently described to produce a disorder characterised by movement disorders, dilated perivascular spaces, and intracranial haemorrhage." (PMID 39191170, 2024).
NIT1 also shares sentences with these, for which no sentence is quoted: adenocarcinoma (2 papers); esophageal adenocarcinoma (1); gastric tumor (1); kidney damage (1); lung adenocarcinoma (1).